IL10 (interleukin 10)
Diseases named in the same sentence as IL10 in open-access papers (continued):
Sharing a sentence is not in itself a finding about the gene and the disease.
tumor (continued). "The biological activities of IL-10 in tumor immunity are extremely controversial and can be highly context-dependent." (PMID 37533789, 2023). "Tumoral cells can indeed promote an elevated production of immunosuppressor cytokines (such as IL-10 and TGFβ1) that downregulate the anti-tumor response at different levels." (PMID 37239941, 2023). "By targeting IL-10, miR-98 prevents HCC from spreading in HCC-conditioned tumor-associated macrophages (TAMs) and by targeting NIK, miR-98-5p prevents HBV-HCC cells from proliferating, migrating, and invading." (PMID 36917438, 2023). "In contrast to the antitumour effects of B cells, Bregs are also a potential target, and Breg-produced IL-10 and IL-35 can have inhibitory effects on a variety of immune cells promoting tumour development." (PMID 36890557, 2023). "Prolonged IL-15 treatment to isolated human intestinal intraepithelial lymphocytes leads to massive production of IFN-γ and IL-10, eventually resulted in enhanced cytotoxicity against tumor cells." (PMID 38106519, 2023). "M2 macrophages secrete epidermal growth factor (EGF), matrix metalloprotein 9 (MMP-9) and the anti-inflammatory factor IL-10 to promote tumor progression." (PMID 36969211, 2023). "While IL-6 promotes the transition of macrophages to a pro-tumor phenotype and promotes the secretion of inflammatory suppressors such as IL-10 and TGF-β." (PMID 37598273, 2023). "Their results indicated that the transferred IL-10 via MSCs was able to prevent the inducement of angiogenesis and tumor growth while increasing the survival of tumor-bearing animals." (PMID 36742134, 2023). "High levels of IL-10 lead to inhibition of tumor metastases, resulting in a slowdown of cell growth." (PMID 37998326, 2023). "IL-35 generally acts jointly with IL-10 in the generation and sustaining of the immunosuppressive tumor microenvironment." (PMID 37958417, 2023). "In HNSCC the M2 phenotype predominates, suppressing T-cell-mediated anti-tumour immunity through the release of IL-10 and TGFβ." (PMID 39935547, 2023). "MDSCs promote tumor progression and enhance tumor cell survival, angiogenesis, invasion, metastasis and production of immunosuppressive cytokines such as IL-10 and TGF-β." (PMID 36875093, 2023). "PGE2 produced by tumor cells promotes IL‐10 production by DCs, thereby inhibiting effector T cell responses." (PMID 36464889, 2023). "IL-10 is generally released by TAMs in the tumor immune microenvironment and contributes to immunosuppression by affecting Treg subpopulations and promoting the release of immunosuppressive factors, including TGF-β." (PMID 37359527, 2023). "For example, TGF-β and IL-10 secreted by M2 macrophages, MDSCs, and tumor cells inhibit CTL activity and enhance TH cell conversion into Tregs." (PMID 37568390, 2023). "A protumorigenic TME is saturated with several supporting tumor growth cytokines like interleukin (IL)-4, IL-6, and IL-10 as well as transforming growth factor (TGF)-β, interferon (IFN)-γ, and chemokines such as chemokine (C-C motif) ligand 2 (CCL2)." (PMID 38033495, 2023). "Studies have suggested that IL-10 is overexpressed in several cancer cells, which can change the tumor microenvironment to enable tumor cells to easily escape from the immune system." (PMID 38102207, 2023). "The changes in (a) CD8, PD-1, PD-L1, TGF-β1 and FOXP3 levels in the tumor nodules and (b) serum levels of IL-2, IL-10 and TGF-β1 in the MTE-treated mice were similar to those in the AOM/DSS mice, as seen by immunohistochemistry." (PMID 37649480, 2023). "Mononuclear myeloid cells secrete large amounts of bioactive lipid products 15(S)-HETEs, which in turn promote the secretion of IL-10 by TAMs and enhance the immunosuppression and immune escape of tumor cells." (PMID 37004014, 2023). "TGF-β and IL-10 released by M2 macrophages can inhibit T cell immune responses and anti-tumor immunity." (PMID 37151887, 2023).
tumor (continued). "TAMs are typically M2-like and polarized by immunosuppressive cytokines such as IL-4, IL-13, or IL-10 in the tumor microenvironment." (PMID 37175092, 2023). "Some studies have also found that tumor-associated macrophage-related molecular markers and secreted cytokines, such as CD163, CD206/CD68, and IL-10, were related to the prognosis of HGSOC." (PMID 37124547, 2023). "In conclusion, S100A9 plays a vital role in the process of IL-10 deficiency-mediated MPE suppression by regulating M1/M2 polarization, thus influencing the tumor-migration capacity and apoptosis." (PMID 37533789, 2023). "PepO-primed M2 macrophages decreased the expression of tumor-supportive molecules like Arg-1, Tgfb, Vegfa and IL-10, and increased the expression of iNOS, Cxcl9, Cxcl10, TNF-α and IL-6 to inhibit TNBC growth." (PMID 37925462, 2023). "IL-10 inhibited effector T cell proliferation, cytokine generation and migration, allowing tumour cells to avoid immune detection." (PMID 37162544, 2023). "Tumor-infiltrating macrophages also serve as the main source of anti-inflammatory cytokine IL-10 to establish an immunosuppressive TME." (PMID 37740232, 2023). "IL10 was shown to contribute to tumor aggressiveness and poor survival in NSCLC, and PD-1 was demonstrated to be a key element in tumor-immune resistance." (PMID 37085672, 2023). "It was observed a significantly higher percentage of PD-1 expression, as well as a higher frequency of IL-10-secreting B cells cultured with tumor cell supernatant (first middle panels)." (PMID 37035195, 2023). "In this context, the levels of GM‐CSF, TNF‐α, IFN‐γ, IL‐1β, IL‐2, IL‐4, IL‐6, IL‐10, and IL‐13 in the peripheral blood of H22 tumor‐bearing mice were detected." (PMID 36043445, 2023). "Large accumulation of TAMs impaired T cell-mediated anti-tumor responses and promoted T cell exhaustion due to IL-10 production and PD-L1 expression." (PMID 37355637, 2023). "First, the immune suppressive cytokines within the tumor microenvironments, including IL-10 and IL-21, were predominant." (PMID 37884996, 2023). "In limited quantities, IL10 has beneficial anti-tumor effects by promoting the maintenance of stem-like CD8 T cells." (PMID 37654482, 2023). "Treg cells contribute to cytotoxic T cell suppression and tumor progression via production of IL10, IL35, and TGF-β." (PMID 36694264, 2023). "In spite of the fact that DCs are essential for immune activation and effector cell recruitment, it has been reported that tumor cells secrete the immunosuppressant cytokine IL-10, which inhibits DC maturation or converts DCs into macrophage-like cells." (PMID 37501719, 2023). "Inflammatory markers like high-sensitivity C reactive protein (hs-CRP), interleukin-10 (IL-10), interleukin-6 (IL-6), and tumor necrosis factor-alpha (TNF-α) reflect the chronic inflammation associated with tumor initiation and progression." (PMID 37764678, 2023). "Tumor-associated macrophages (TAMs) are among these immune subtypes and can be polarized to M2 by IL-13, IL-4, TGF-β, or IL-10, within the TME." (PMID 36860731, 2023). "With respect to the gene expression profile, CCL21 increased the expression of tumor-supportive genes such as Vegfa, Mrc1, Arg1, and Cd274 (PD-L1) in microglia, as well as in BMDMs that also showed increased expression of Il-10 and Tgfβ1." (PMID 37314567, 2023). "IL-10 can maintain the immune response at bay and prevents the elimination of tumor cells because it counterattacks the cytotoxic functions in macrophages." (PMID 37283734, 2023). "Previous research shows that TGF-β and IL-10 can suppress T lymphocytes activity and proliferation, resulting in the failure of immunological responses against tumor." (PMID 37253929, 2023). "Significant declines in MPE volume and tumor mass were observed in the IL-10−/− group compared to the WT control group (left two panels)." (PMID 37533789, 2023).
tumor (continued). "TGF-β and IL10 induce the conversion of resident fibroblasts into cancer-associated fibroblasts (CAF) and monocytes into tumor-associated macrophages (TAM), respectively." (PMID 37828948, 2023). "On the other hand, the anti-inflammatory cytokine IL-10 was known to influence PTC’s aggressiveness by inhibiting immune cells’ anti-tumor activity." (PMID 37563607, 2023). "They operate through an IL10-dependent pathway to induce T-cell dysfunction, creating conditions that lead to tumor progression." (PMID 37046842, 2023). "In contrast, M2 macrophages exhibit pro-tumor activities and produce immunosuppressive cytokines such as IL-4, IL-10, and transforming growth factor-β (TGF-β)." (PMID 37510993, 2023). "An important parameter describing the relationship between the tumor and its microenvironment (in particular, the immune microenvironment) is the production of IL-10, a cytokine with an immunosuppressive effect." (PMID 36986829, 2023). "Overall, our results demonstrated that, despite a lack of anti-tumoral efficacy of mifamurtide treatment against aggressive and metastatic OS tumor cells, mifamurtide efficacy can be potentiated by the administration of an IL-10 blocking antibody." (PMID 37835437, 2023). "Meanwhile, Th2 cells secrete IL-4 and IL-10, which promote tumor growth or metastasis through immunosuppression." (PMID 37077908, 2023). "These two complementary signals lead to the activation of STA3 and NFkB transcription factors resulting in blocking IL‐12 secretion in favour of IL‐10 and IL‐6 release, such as described for tumour cells." (PMID 38117000, 2023). "IL-10 can be produced by most T cells (including Treg cells), DCs, macrophages, epithelial cells and tumor cells." (PMID 37483629, 2023). "M2 macrophages, on the other hand, activated by IL-4, IL-10, and IL-13, promote tumor growth and suppress anti-tumor immune responses." (PMID 38201551, 2023). "Tumor cells can secrete IL10, CXCL8, and TGFB1, which directly reduce NK cell cytotoxic functions and/or recruit other immune cells such as Treg cells, MDSCs, CD11b + Ly6G + neutrophils, and DC, thus inhibiting NK cell functions indirectly." (PMID 37190251, 2023). "Tumor cell-derived cytokines (such as IL-6, IL-10, IFN-γ and TGF-β) and chemokines (such as CCL2, CCL5 and CXCL4) are key regulators of macrophage polarization." (PMID 37833255, 2023). "Still, regarding the effect of CTX on the secretion of cytokines detected in the ascitic fluid or in the peritoneal lavage, the concomitant administration to the inoculation of tumor cells inhibited the secretion of IL-10 on the 6th day." (PMID 37888647, 2023). "HIF-1 also suppresses the anti-tumor immune response by inducing Tregs, myeloid-derived suppressor cells (MDSCs), and immunosuppressive cytokines such as IL-10 and transforming growth factor-beta (TGF-beta)." (PMID 37664112, 2023). "Intratumoral microbiota enhanced the secretion of specific chemokines (e.g., C-C motif chemokine ligand 2 (CCL2), CCL4, CXCL1 and CXCL10) and interleukins (e.g., IL-1β, IL-6 and IL-10) into the surrounding milieu, leading to T cell exclusion and tumor growth." (PMID 37868956, 2023). "PBT treatment reduced tumor growth in mice and increased levels of cytokines such as IL-10, MCP-1, and IFN-γ, which are associated with enhanced immune activity in tumors and tumor microenvironments." (PMID 38169949, 2023). "Several inflammatory factors related to tumours, including interleukins (IL-6, IL-10, IL-17, IL-1β), TGF-β, IFN-γ, TNF-α, VEGF, and MMPs, are also the cancer-associated genes." (PMID 37742025, 2023). "Other groups have shown that IL-10 expression is higher in tumor-derived MSCs than in healthy tissue and that the expression of IL-10 by BM-MSCs does not modify the expression of other inflammatory molecules." (PMID 37048119, 2023).
tumor (continued). "The results indicated that overexpressed mir-21-5p can induce the production of IL-10 in a high level and promote the proliferation of tumor cells, consistent with our previous studies." (PMID 36902024, 2023). "Regarding IL-10’s role as a tumor promoter, it is thought that it promotes immune escape from the tumor by inhibiting antigen presentation and thus decreasing the antitumor immune response in the TME." (PMID 36771154, 2023). "IL1RN and IL10 have anti-inflammatory functions, IL1 promotes inflammation, carcinogenesis and anti-tumor immunity, IL6 is pro-tumoral by activating carcinogenesis and tumor outgrowth, and IL10 promotes cytotoxicity but inhibits anti-tumor activities." (PMID 37465363, 2023). "Tumor-derived cytokines, such as IL-10 or TGF-β, represent other major mechanisms of cancer-induced immunosuppression." (PMID 37894728, 2023). "Among the genetic factors, Interleukin-10 (IL-10) is one of the anti-inflammatory cytokines as well as a multifunctional cytokine, which can inhibit development of tumour and disease progression." (PMID 37684564, 2023). "DC morphological changes induced by biochemical factors were reported in our previous studies, and mainly included tumor-derived cytokines, such as IL-10, TGF-β1, and VEGF." (PMID 36826287, 2023). "Conversely, Peli1-mediated K63-linked ubiquitination of IRAK1 and STAT1 activation inhibits IL-10-induced polarization of M2c macrophages and IL-10 production, thereby inhibiting tumor growth." (PMID 38179042, 2023). "We also elucidated the inflammation levels in the tumor tissues of each group and observed that the mRNA expression of IL-1β and IL-8 was increased but that of IL-10 decreased after LINC00174 overexpression." (PMID 37448887, 2023). "AMs have been shown to promote a pro-tumorigenic NSCLC microenvironment via direct the secretion of anti-inflammatory IL10 or the enhancement of TGFβ secretion by tumor cells." (PMID 37830618, 2023). "IL-10, an immunosuppressive cytokine, can hinder the function of effector T cells and antigen-presenting cells, potentially fostering tumor growth by curbing antitumor immunity." (PMID 37895855, 2023). "Under hypoxia, ILC2s can transdifferentiate into an IL-10+ ILC immunosuppressive phenotype similar to that of regulatory T cells and are implicated with tumor progression in the hypoxic environments of pancreatic ductal adenocarcinoma (PDAC)." (PMID 37514187, 2023). "Conversely, the M2‐type macrophages, which are induced by the type 2 T helper cell (Th2) cytokines, such as interleukin (IL)‐4, IL‐10, or IL‐13, promote angiogenesis, tumor growth, and metastasis." (PMID 36794651, 2023). "In this dormant stage, a balance between anti-tumor (IL-12 and IFN-γ) and tumor-promoting cytokines (IL-10 and IL-23) is established." (PMID 37046762, 2023). "Brown or yellow colour indicated positive IL-6, IL-8 and IL-10 staining on the cell membrane or in the cytoplasm of tumor cells." (PMID 36693957, 2023). "TAMs are usually found to exhibit a tumor-promoting phenotype by producing immune suppressive cytokines such as IL-6, IL-10, and TGF-β, and they represent a large population of cells with immunosuppressive function in TME." (PMID 38239396, 2023). "The canonical WNT–β-catenin pathway has been implicated in hindering anti-tumor immune responses and fostering an immunologically “cold” TME by inducing the production of immunosuppressive IL-10 by tumor cells." (PMID 37345111, 2023). "The contradictory roles of IL-10 are likely contingent upon environmental cues and individual tumor characteristics, further complicating potential therapeutic interventions aimed at altering IL-10 pathways." (PMID 36768342, 2023). "Secretion of cytokines, such as anti-inflammatory IL-10 and transforming growth factor β (TGFβ), is involved in the establishment of a tumor-favorable immune suppressive microenvironment." (PMID 37345186, 2023).
tumor (continued). "We next characterized CD24hiIgDlo/–CD38lo and CD24hiIgDlo/–CD38hi IL-10+ Bregs in tumor-bearing mice and their responses to FGK or GSK." (PMID 37291146, 2023). "High amounts of VEGF and IL-10 in tumorigenic M2-like TAMs stimulate angiogenesis and speed up the immunological escape of tumor cells." (PMID 37138860, 2023). "Interleukin-10 is secreted by macrophages and tumor cells, which inhibits cytotoxic T-cells and suppresses the immune response contrary to the tumor." (PMID 37298889, 2023). "Macrophages are polarized into the M2 type in the presence of IL4 or IL10, which promote tumour progression through complex autocrine and paracrine pathways." (PMID 35999359, 2023). "M2 macrophages secrete TGF-β and IL-10 to suppress anti-tumor immunity and induce angiogenesis, thereby shifting to an environment favorable for cancer cell proliferation." (PMID 37626816, 2023). "IL-10 is currently emerging as a previously unappreciated regulator of antitumor function and a master switch of tumor-promoting inflammation to antitumor immunity." (PMID 36581713, 2023). "M2-macrophages exert immunosuppressive functions by promoting the expression and secretion of immunosuppressive cytokines such as TGF-β 1 and IL-10, thereby promoting tumor progression and metastasis." (PMID 37588995, 2023). "Genetic inactivation of PPARδ in B cells impaired the development and function of IL-10+ B cells, and treatment with PPARδ inhibitor diminished the induction of IL-10+ Bregs by tumor and CD40 engagement." (PMID 37291146, 2023). "We observed that non-responders showed elevated levels of proinflammatory mediators, such as IL-1RA, IL-6, IL-8 and to lesser extent IL-10, which are associated with STAT3 activation and tumor immunosuppression." (PMID 38259453, 2023). "This increase in IL10 coincides with decreasing proinflammatory cytokines, creating a more favorable environment for tumor growth." (PMID 36968140, 2023). "Cytokine ELISA showed decreased levels of IL-10 but stable levels of IFN gamma in the tumor microenvironment." (PMID 37835464, 2023). "Conversely, mediators released by mast cells such as FGF-2, NGF, PDGF, VEGF, IL-8, and IL-10 can promote the expansion of tumor cells." (PMID 36793597, 2023). "TAMs, especially M2-type TAMs, produce a large number of anti-inflammatory factors, including IL-10, which leads to an immunosuppressive microenvironment and orchestrates tumor growth." (PMID 37064877, 2023). "Tumor-derived exosomes enhance Breg proliferation and increase their resistance to apoptosis through mechanism dependent on IL10 and TGF-β, which later inhibit CTLs activities." (PMID 37915578, 2023). "In this study, an unexpected result of consuming VSL#3 probiotic was the lack of an inhibitory effect on tumorigenesis and the tendency to enhance tumor invasion in AOM/Il10−/− mice." (PMID 37719797, 2023). "Tregs suppress the function of APCs, B cells, NK cells, and tumor-specific effector T cells by direct cellular interaction or by secretion of anti-inflammatory cytokines (e.g., IL-10 and TGF- β) and cytolytic granules (e.g., granzymes, perforins)." (PMID 38213954, 2023). "Conversely, Treg-produced IL-10 was reported to suppress Th17-induced inflammation in the tumor microenvironment in mice by preventing Th17 proliferation in the tumor and spleen." (PMID 37235332, 2023). "After being shaped by the microenvironment of draining lymph nodes, B cells promoted tumor growth in an IL-10-independent manner." (PMID 37234990, 2023). "In particular, glioma-associated macrophages (GAM) in situ are pro-tumor by secreting M0-M2-like growth factors such as VEGF, IL-10, and other factors at the periphery of the growing tumor, and more M1-like in the necrotic core region." (PMID 36982186, 2023).